Y_RNA (Y RNA )
Gene: Miscellaneous RNA gene on chromosome 18 (50,959,267 to 50,959,379, reverse strand). Ensembl gene ENSG00000200752.
Homologues: Orthologues: chimpanzee Y_RNA (99% identical), macaque Y_RNA (92% identical). Paralogues in human: Y_RNA (84% identical), RNY1 (83% identical), RNY1P11 (83% identical), Y_RNA (83% identical), Y_RNA (82% identical), Y_RNA (81% identical), RNY1P10 (80% identical), RNY1P8 (80% identical), Y_RNA (80% identical), Y_RNA (79% identical), Y_RNA (78% identical), Y_RNA (77% identical), and 95 more.